C19orf44 (chromosome 19 open reading frame 44)
Synonyms: FLJ21742; FCAP71
Tractability: PROTAC: ubiquitination databases record sites on it.
Gene: Protein-coding gene on chromosome 19 (16,496,394 to 16,521,369, forward strand). Ensembl gene ENSG00000105072.
Subcellular location (Human Protein Atlas): Nucleoplasm; Cytosol; Golgi apparatus; Nuclear bodies; Primary cilium
Gene Ontology:
Molecular function: protein binding
Genetic constraint (gnomAD): Loss-of-function variants: 40 observed, 45.56 expected, observed/expected ratio (o/e) 0.88, 90% interval 0.68 to 1.14. The upper end of that interval is the gene's LOEUF score, 1.14, which puts it in group 5 of 6, group 1 being the genes least tolerant of losing a copy. Missense variants: 691 observed, 830.98 expected, observed/expected ratio (o/e) 0.83, 90% interval 0.78 to 0.88. Synonymous variants: 293 observed, 331.02 expected, observed/expected ratio (o/e) 0.89, 90% interval 0.8 to 0.98.
Homologues: Orthologues: chimpanzee C19H19orf44 (99% identical), macaque C19H19orf44 (89% identical), pig C19orf44 (60% identical), dog C19orf44 (59% identical), rabbit C19orf44 (51% identical), rat C16h19orf44 (50% identical), mouse 1700030K09Rik (49% identical), tropical clawed frog c1h19orf44 (24% identical), zebrafish si:ch1073-104i17.1 (11% identical).
Diseases named in the same sentence as C19orf44 in open-access papers:
C19orf44 is named in the same sentence as 1 disease in open-access papers, as found by Europe PMC text mining. Sharing a sentence is not in itself a finding about the gene and the disease.
C19orf44 shares sentences with these, for which no sentence is quoted: cancer (1 paper).